BCL3 (BCL3 transcription coactivator)
Diseases named in the same sentence as BCL3 in open-access papers (continued):
Sharing a sentence is not in itself a finding about the gene and the disease.
renal fibrosis (2 papers, 2017 to 2023). A final common manifestation of a wide variety of chronic kidney diseases characterized by glomerulosclerosis and tubulointerstitial fibrosis. "Thus, the quantitative examination of serum Bcl-3 protein in additional CKD patients is needed to determine the diagnostic significance of Bcl-3 in renal fibrosis." (PMID 29228604, 2017). "In the present study, Bcl-3 was markedly up-regulated in the early stages of renal fibrosis in the UUO mouse model." (PMID 29228604, 2017). "The results of this study suggest that Bcl-3 can be a valuable clinical biomarker of renal fibrosis in CKD." (PMID 29228604, 2017). "Serum levels of Bcl-3 protein increased earlier than serum HE4 in the UUO mouse model, suggesting that Bcl-3 was more sensitive than HE4 as a biomarker of renal fibrosis." (PMID 29228604, 2017). "Compared with controls, the Bcl-3 mRNA levels showed a persistently significant increase from the beginning of UUO-induced renal fibrosis." (PMID 29228604, 2017). "Nevertheless, we provided the evidence that Bcl-3 could serve as a novel biomarker of renal fibrosis to monitor the disease progression in CKD, particularly in combination with other markers such as HE4 in the non-cancerous patients." (PMID 29228604, 2017). "We have previously shown that Bcl-3 regulates the TGFβ signaling and hypothesized that Bcl-3 might be involved in renal fibrosis." (PMID 29228604, 2017). "The ROC analysis suggested that Bcl-3 was better than HE4 as a biomarker of renal fibrosis." (PMID 29228604, 2017). "ROC curve analysis indicated that Bcl-3 might be better than HE4 as a biomarker of renal fibrosis in CKD." (PMID 29228604, 2017). "In the patients with CKD the serum Bcl-3 level was significantly higher than in healthy controls and was highly correlated with the serum level of HE4, a recognized biomarker for renal fibrosis and renal dysfunction." (PMID 29228604, 2017). "Serum protein levels of Bcl-3 and HE4 rose with the development of renal fibrosis in UUO mouse model." (PMID 29228604, 2017). "To evaluate the value of Bcl-3 and HE4 served as biomarkers of renal fibrosis, we tested the levels of serum Bcl-3 and HE4 protein in the UUO model using western blotting due to a lack of reliable commercially available quantitative ELISA kits for mouse Bcl-3 and HE4." (PMID 29228604, 2017). "Compared with renal tissues in sham-operated mice, increases in Bcl-3 mRNA and protein in the renal tissues in the UUO model were accompanied with increases in other markers of renal fibrosis, including human epididymis protein 4 (HE4), a recently identified biomarker of renal fibrosis." (PMID 29228604, 2017). "Bcl-3 protein was detectable in the sera of Bcl-3 WT mice, but not in the sera of Bcl-3 KO mice, and serum Bcl-3 protein levels gradually increased with the progression of renal fibrosis." (PMID 29228604, 2017). "Indeed, Bcl-3 protein was also detected in the supernatant of tumor cells expressing high levels of Bcl-3 (data not shown), suggesting that Bcl-3 may also be induced during renal fibrosis and autonomously released into the serum in the exosome pellet." (PMID 29228604, 2017). "Although the combination of serum Bcl-3 and HE4 was not better than Bcl-3 alone using western blotting in CKD patients, a quantitative measure of serum Bcl-3 and HE4 is needed to re-evaluate the value of the combination of Bcl-3 and HE4 in the detection of renal fibrosis in CKD patients." (PMID 29228604, 2017).
Acute hepatitis (1 paper, 2022). Acute hepatic injury resulting from inflammation typically accompanied by increased serum alanine transaminase activity. "As plant lectin concanavalin A (ConA) is another widely used mouse model for introducing immune-mediated acute hepatitis by inducing TNFα, IL-6 and IFNγ, we further detected the role of Bcl-3 in ConA-induced liver injury." (PMID 34853447, 2022).
acute kidney injury (1 paper, 2022). Sudden and sustained deterioration of the kidney function characterized by decreased glomerular filtration rate, increased serum creatinine or oliguria. "Bcl-3 was the most upregulated NF-κB-related gene in experimental acute kidney injury, and it was also one of the most upregulated genes in renal tubular cells stimulated by TWEAK." (PMID 35355979, 2022).
allergic asthma (1 paper, 2024). A asthma with a basis in a pathological type I hypersensitivity reaction. "Since it was already shown that Bcl-3 is a negative regulator for IL-10, these results indicate that Bcl-3 is a critical inhibitor of IL-10 in allergic asthma and targeting the Bcl-3/IL-10 axis may be a promising approach for allergic asthma therapy." (PMID 38172451, 2024).
brain ischemia (1 paper, 2023). Diminished or absent blood supply to the brain caused by obstruction (thrombosis or embolism) of an artery resulting in neurologic damage. "And the downstream target gene Bcl-3 as a nuclear member of the inhibitor of the κB family is related to brain ischemia in rats." (PMID 37684515, 2023).
colon adenocarcinoma (1 paper, 2015). "In addition, Bcl-3 expression and localization in colon adenocarcinoma cells were analysed by western blot, immunohistochemistry and subcellular fractionation separately." (PMID 25929479, 2015).
colorectal adenoma (1 paper, 2016). An adenoma that arises from the colon or rectum. "BCL-3 expression was also assessed in a panel of colorectal adenoma-derived and carcinoma-derived cell lines by western blotting." (PMID 26033966, 2016). "The role of BCL-3/NF-κB complexes on cell growth was studied in vivo and in vitro using an siRNA approach and exogenous BCL-3 expression in colorectal adenoma and carcinoma cells." (PMID 26033966, 2016). "As the pro-survival action of BCL-3 was also demonstrated in colorectal adenoma-derived cells, results suggest that targeting BCL-3 function may be effective both in the prevention and treatment of cancer." (PMID 26033966, 2016).
contact dermatitis (1 paper, 2015). An inflammatory skin condition caused by direct contact between the skin and either an irritating substance or an allergen. "Increased Bcl3 expression occurs in a variety of cancers and some non-cancer-related inflammatory skin conditions such as contact dermatitis." (PMID 26413810, 2015).
cutaneous T-cell Lymphoma (1 paper, 2024). "In cutaneous T-cell Lymphoma knockdown of Bcl-3 decreases the expression of cIAP1 and cIAP2, resulting in reduced cell survival." (PMID 39327470, 2024).
cyst (1 paper, 2022). A sac-like closed membranous structure that may be empty or contain fluid or amorphous material. "At 21 days PI, overall inflammation and cyst burden were both higher in both complete Bcl3 KO mice and Bcl3flx/flxZbtb46 cre mice compared to infected wildtype mice." (PMID 36318581, 2022).
ductal carcinoma (1 paper, 2022). "Interestingly, cytoplasmic BCL3 was significantly related to RFS in lobular carcinoma, whereas nuclear BCL3 was prognostic for ductal carcinoma as well." (PMID 35020071, 2022).
endometrioid adenocarcinoma (1 paper, 2024). An adenocarcinoma characterized by the presence of malignant glandular epithelial cells resembling endometrial cells. "Since Bcl3 gene expression is significantly increased in ovarian clear-cell adenocarcinoma, endometrioid adenocarcinoma, ovarian mucinous adenocarcinoma, ovarian serous adenocarcinoma and ovarian serous surface papillary carcinoma, Bcl3 might serve as a potential novel biomarker in OC." (PMID 39123403, 2024).
esophageal tumors (1 paper, 2021). "Since IL6 overexpression is only observed in ESCC samples, while BCL3 higher mRNA levels are detected both in tumor-surrounding mucosa and esophageal tumors, paracrine IL6 signaling could be responsible for BCL3 induction in tumor-adjacent tissue." (PMID 34422669, 2021).
Glanzmann thrombasthenia (1 paper, 2011). "In this regard, previous studies from our group showed that platelets from patients with Glanzmann Thrombasthenia, which lack integrin αIIbβ3, do not synthesize Bcl-3." (PMID 22069700, 2011).
influenza (1 paper, 2025). An acute viral infection of the respiratory tract, occurring in isolated cases, in epidemics, or in pandemics; it is caused by serologically different strains of viruses (influenzaviruses) designated A, B, and C, has a 3-day incubation period, and usually lasts for 3 to 10 days. "Although it was reported that BCL-3 deficiency affects T cell-dependent immunity against IAV, the role of this protein on the anti-influenza innate immune response triggered by respiratory epithelial cells has not been investigated before." (PMID 40565228, 2025).
injury (1 paper, 2025). Damage inflicted on the body as the direct or indirect result of an external force, with or without disruption of structural continuity. "To investigate whether Bcl3 plays a role in APAP-induced liver injury, we measured the hepatic expression of Bcl3 in a mouse model of APAP-induced liver injury." (PMID 40015625, 2025).
ischaemic stroke (1 paper, 2021). "Previously, we identified the human orthologues for a number of rat genes, which expression was changed after ischaemic stroke (Adora2a, Bcl3, Ccl22, Ccr1, Cd14, Gpr6, Gpr88, Rgs9, and other genes)." (PMID 34946819, 2021).
Lewis lung carcinoma (1 paper, 2024). "Moreover, conditioned media from B16-F10, 4T1 or Lewis lung carcinoma (LLC) cultures similarly induced PIM3, INHBB and BCL3 expression, indicating that secreted factors of multiple cancer cell types induced rCap marker expression in cultured ECs." (PMID 39627185, 2024).
liver failure (1 paper, 2022). A liver disease characterized by the liver losing or has lost all of its function. "Our findings uncover a remarkable function of Bcl3 in controlling liver regeneration, which indicates that Bcl3 may be a potential therapeutic target in the promotion of liver regeneration and prevention of liver failure." (PMID 35351855, 2022).
lymph node disease (1 paper, 2019). "Interestingly, NF-κΒ2/ Bcl3 “co-expression” was associated with lymph node infiltration, with concurrent signal for both molecules being higher in patients without lymph node disease (P = 0.014)." (PMID 31586084, 2019).
lymph node metastasis (1 paper, 2022). "In multivariate Cox regression, we adjusted the hazard ratio (HR) of cytosolic and nuclear BCL3 for the parameters ER status and lymph node metastasis." (PMID 35020071, 2022).
malignant peritoneal mesothelioma (1 paper, 2021). An aggressive malignant mesothelioma that arises from the peritoneum. "Ultimately, in vivo validation of the role of PD-1 and BCL3 in CD8+ T cells can be studied using malignant peritoneal mesothelioma mouse models through silencing of PD1 and/or BCL3 and measuring the functional activity of CD8+ T cells." (PMID 34500467, 2021).
monocytic leukemia (1 paper, 2019). "Furthermore, a mildly increased incidence of high BCL3 expression was observed in M4/M5 subtypes of acute myelomonocytic/monocytic leukemia." (PMID 30357752, 2019).
multiple sclerosis (1 paper, 2022). A progressive autoimmune disorder affecting the central nervous system resulting in demyelination. "Another study suggests that low Bcl-3 expression is associated with an increased risk of multiple sclerosis, indicating the complexity of Bcl-3 action." (PMID 36159779, 2022).
myocardial infarction (1 paper, 2019). Gross necrosis of the myocardium, as a result of interruption of the blood supply to the area, as in coronary thrombosis. "Six hub genes, including BCL3, HCK, PPIF, S100A9, SERPINA1, and TBC1D9B that differentiated on admission after myocardial infarction the HF patients from the non-HF ones, can serve as early prognostic biomarkers of post-AMI patients." (PMID 31850068, 2019).
nasopharyngeal tumors (1 paper, 2021). "More recently, the role of BCL3 in solid tumors started to be elucidated, and its overexpression, observed in breast and nasopharyngeal tumors, seems to be induced by NF-κB activation and EBV latent genes, respectively." (PMID 34422669, 2021).
Oral Carcinomas (1 paper, 2025). "While the role of B-cell lymphoma 3 (BCL3)-encoded protein as an oncogene has been explored in other epithelial cancer types, its specific contribution to oral carcinoma (OC) remains insufficiently investigated." (PMID 40486320, 2025).
osteoarthritis (1 paper, 2025). A noninflammatory degenerative joint disease occurring chiefly in older persons, characterized by degeneration of the articular cartilage, hypertrophy of bone at the margins and changes in the synovial membrane. "Our integrative approach coupled with experimental validation uncovered BCL3 as a biomarker indicative of the role of a PCD mechanism underlying osteoarthritis." (PMID 39676743, 2025).
osteosarcoma (1 paper, 2019). A usually aggressive malignant bone-forming mesenchymal neoplasm, predominantly affecting adolescents and young adults. "As another predicted regulator of the identified DEGs, B cell lymphoma 3 (Bcl3) has been shown to promote wound healing as its knockdown resulted in significantly reduced cell proliferation and migration in the human osteosarcoma U2OS line." (PMID 32082384, 2019).
ovarian clear cell adenocarcinoma (1 paper, 2024). A malignant glandular epithelial neoplasm characterized by the presence of clear and hobnail cells. "Bcl3 gene expression is increased in ovarian clear-cell adenocarcinoma, ovarian endometrioid adenocarcinoma, ovarian mucinous adenocarcinoma, ovarian serous adenocarcinoma, and ovarian serous surface papillary carcinoma." (PMID 39123403, 2024).
ovarian serous cystadenocarcinoma (1 paper, 2022). A malignant serous cystic epithelial neoplasm arising from the ovary. "Positive correlations were found between the mRNA levels of BCL3 with some of these target genes, such as TNFAIP3/A20, CCL2, CD274, and CXCL10, in brain lower grade glioma (LGG) and ovarian serous cystadenocarcinoma (OV) samples from TCGA database." (PMID 35990614, 2022).
pancolitis (1 paper, 2020). Ulcerative colitis that involves the entire colon. "As a further illustration of the potential context-dependent function of BCL-3, another recent study showed that Bcl-3 overexpression, specifically in CD4+ T cells (including T regulatory cells), results in a pancolitis of the large bowel of mice." (PMID 31930327, 2020).
pancreatic tumours (1 paper, 2024). "In the other study BCL3 was shown to have a tumour suppressive role in pancreatic cancer, reducing the cancer stem cell compartment in these tumours." (PMID 38195591, 2024). "However, one report describes an inverse relationship between BCL3 and cancer stemness, in which BCL3 appears to reduce the CSC compartment within pancreatic tumours, which highlights the heterogeneous nature of CSCs originating from different tissues." (PMID 38195591, 2024).
plasmacytoma (1 paper, 2009). Plasmacytoma is a localized mass of neoplastic monoclonal plasma cells that represents approximately 5% of all plasma cell neoplasms. "We also examined the expression of Bcl-3 at protein level by immunohistochemical staining of biopsies from MM patients and patients with plasmacytoma, and found that 11% (two of 18) of the biopsies stained positive for Bcl-3." (PMID 19191868, 2009).
Promyelocytic Leukemia (1 paper, 2024). "In the G2M Checkpoint hallmark, genes such as B-Cell Lymphoma 3 (BCL3), Cyclin C (CCNC), and Promyelocytic Leukemia (PML) are downregulated under Fe ion irradiation conditions compared to photon irradiation conditions." (PMID 39286254, 2024).
psoriasis (1 paper, 2021). An autoimmune condition characterized by red, well-delineated plaques with silvery scales that are usually on the extensor surfaces and scalp. "While Bcl-3 inhibitors have been extensively studied as potential therapeutics in cancer, their role as a therapeutic in psoriasis or other skin diseases has not yet been explored." (PMID 34012438, 2021). "By targeting Bcl-3, both CD4+ and CD8+ TRM disease pathways in psoriasis could be interrupted." (PMID 34012438, 2021).
rectal cancer (1 paper, 2022). A primary or metastatic malignant neoplasm that affects the rectum. "This work furthers our understanding of therapeutic resistance in CRC and offers a rationale for targeting BCL-3 as an adjuvant to conventional therapies, particularly in the setting of neo-adjuvant therapy for locally advanced rectal cancer." (PMID 35468497, 2022).
renal carcinoma (1 paper, 2024). A carcinoma arising from the epithelium of the renal parenchyma or the renal pelvis. "BCL3 and EP300 as prognostic factors for KIRC, and upregulated RUNX1 is closely associated with renal cancer progression." (PMID 38292868, 2024).
sarcoidosis (1 paper, 2020). Sarcoidosis is a multisystemic disorder of unknown cause characterized by the formation of immune granulomas in involved organs. "Eight upregulated transcripts were common to sarcoidosis lung granulomas (CSF3, SERTAD1, MMP9, CCL19, BCL3, AREG, PTGS, F3)." (PMID 33276795, 2020).
skin papilloma (1 paper, 2018). A benign papillary neoplastic growth on the skin composed of epithelial cells and a fibrous stalk. "This correlates with increased Bcl-3 expression in late stage skin papillomas and SCC, suggesting a role for the p50:p50:Bcl-3 complex in tumour promotion." (PMID 30205516, 2018).
thyroid cancer (1 paper, 2023). "For example, one study reported that genetic variants of ferroptosis‐related APOE, BCL3, and ALOX5AP were associated with the risk of thyroid cancer." (PMID 38151984, 2023).
toxoplasmosis (1 paper, 2022). A parasitic disease contracted by the ingestion or fetal transmission of toxoplasma gondii. "We have extended our previous studies of Bcl3 in toxoplasmosis by assigning a specific role in Xcr1+ cDC1 cells for antigen presentation and CD8+ T cell activation, possibly resulting from Bcl3-dependent effects on antigen cross presentation." (PMID 36318581, 2022). "Finally, our single cell RNAseq data suggest that the effect of Bcl3 deficiency on cDC gene expression in the model includes major effects on antigen processing genes, which provide new and testable hypotheses for future studies of the functional role of Bcl3 in toxoplasmosis." (PMID 36318581, 2022).
triple-negative breast carcinoma (1 paper, 2024). An invasive breast carcinoma which is negative for expression of estrogen receptor (ER), progesterone receptor (PR), and human epidermal growth factor receptor 2 (HER2). "This has been reported in MDA-MB-468 triple negative breast cancer cells following BCL3-shRNA mediated suppression but the underlying transcriptional mechanism and c-Myc promoter binding sites responsible for this regulation have not been elucidated." (PMID 38195591, 2024). "One study reported BCL3 as prognostic for improved survival in a specific subtype of triple negative breast cancer patients and in a representative cell line, where BCL3 was shown to improve responses to paclitaxel, while still displaying its conventional oncogenic role in promoting proliferation." (PMID 38195591, 2024). "Furthermore, pharmacological suppression of BCL3 systemically in mice inhibited both the experimental metastatic seeding of human triple negative breast cancer (MDA-MB-231) cells and the spontaneous metastasis of syngeneic mammary 4 T1.2 cells in vivo." (PMID 38195591, 2024). "Suppression of BCL3 led to the upregulation of TNF-alpha and IL-6 and the downregulation of IL-10 in MDA-MB-231 triple-negative breast cancer cells, all of which would theoretically stimulate the recruitment and activation of immune cells within the tumour microenvironment." (PMID 38195591, 2024).
Ureteral obstruction (1 paper, 2017). Obstruction of the flow of urine through the ureter. "Whole-transcriptomic analysis of renal tissues in a unilateral ureteral obstruction (UUO) mouse model revealed that the mRNA level of Bcl-3, an atypical member of the IκB family, was induced 6.3-fold 2 days after UUO." (PMID 29228604, 2017).